MIR1972-1 (microRNA 1972-1)
Synonyms: hsa-mir-1972; MIR1972; hsa-mir-1972-1
Gene: MicroRNA gene on chromosome 16 (15,010,321 to 15,010,397, reverse strand). Ensembl gene ENSG00000238728.
Homologues: Paralogues in human: MIR1972-2 (100% identical).